SRSF3 (serine and arginine rich splicing factor 3)
Diseases named in the same sentence as SRSF3 in open-access papers (continued):
Sharing a sentence is not in itself a finding about the gene and the disease.
colorectal cancer (continued). "SRSF3 could modulate the usage of MAP4K4 exon 16′ in a sequence specific manner, while the inclusion of SRSF3 exon 4′could be enhanced by RBM4 in colorectal cancer cells." (PMID 33072610, 2020). "Interestingly, there are contradictory reports on the expression and function of SRSF3 in colorectal cancer." (PMID 33072610, 2020). "By screening compounds from commercial databases, SFI003, among dozens of its derivatives, has been found to be the most potent inhibitor on SRSF3 activities, with a lowest IC50 value, in colorectal cancer cells." (PMID 37416784, 2023). "SRSF3 increases the expression of the EMT-related genes N-cadherin and vimentin, thus promoting the invasion and migration of colorectal cancer (CRC) cells." (PMID 32284746, 2020). "SRSF3 is negative or weakly positive expressed in 80% patients with metastatic stage IV, which was markedly related to poor survival in colorectal cancer." (PMID 33072610, 2020). "Using a RAC1 minigene in HT29 colorectal cancer (CRC) cells, Gonçalves and coworkers found that the splicing factor SRSF3 (formerly SRp20) increased skipping of alternative exon 3b, whereas another splicing factor, SRSF1 (formerly ASF/SF2), increased its inclusion." (PMID 30621237, 2019). "Notably, SRSF3, CPSF3, FIP1L1, CTR9, NUDT21, and CSTF2, among others, were found to exhibit a more significant contribution to the differential 3′-UTR gene expression in colorectal cancer." (PMID 40702779, 2025). "However, it was found that SRSF3 was significantly upregulated in a normal colon, but it had different expression levels (negative to strong) in colorectal cancer tissues." (PMID 33072610, 2020).
hepatocellular carcinoma (21 papers, 2015 to 2026). A malignant tumor that arises from hepatocytes. "To test whether loss of SRSF3 could directly cause DNA damage, we knocked down SRSF3 expression in human HepG2 hepatoma cells in vitro and observed increased expression of γ‐H2A.X." (PMID 35615981, 2022). "The genetic deletion of SRSF3 in mouse hepatocytes impairs hepatic lipid and glucose metabolism and leads to fibrosis and formation of hepatocellular adenoma that progresses to hepatocellular carcinoma." (PMID 41480745, 2026). "Srsf3 knockout in mice appears to induce hepatocellular carcinoma 91 and overexpression of SRSF3 suppresses hepatocellular carcinoma cell proliferation." (PMID 37416784, 2023). "SRSF3 also affects the expression of spliced variant coiled-coil domain containing 50 short (CCDC50S) to contribute to the growth and metastasis of hepatocellular carcinoma (HCC) through the Ras/Foxo4 signaling pathway." (PMID 35198444, 2022). "Later, in human hepatocellular carcinoma cells, SRSF3 was found to be dephosphorylated and inactivated." (PMID 34917618, 2021). "However, IR (Ionizing Radiation)-induced SRSF3 downregulation resulted in elevated levels of the splice isoform PRMT5S to inhibit hepatocellular carcinoma progression." (PMID 40129567, 2025). "In contrast to most cancers, the role of SRSF3 in hepatocellular carcinoma is complicated." (PMID 37416784, 2023). "However, it has been reported that specific depletion of SRSF3 in hepatocytes leads to hepatocellular carcinoma in mice." (PMID 37558679, 2023). "In addition, lnc-AROD can enhance hepatocellular carcinoma proliferation by interacting with serine- and arginine-rich splicing factor 3 (SRSF3) to trigger pyruvate kinase M (PKM) switching from PKM1 to PKM2 (23, –, 25)." (PMID 37036350, 2023). "However, specific knockout of SRSF3 in mouse hepatocytes impaired hepatocyte maturation and metabolism and induced spontaneous hepatocellular carcinoma." (PMID 34917618, 2021). "We showed that the PPM1G, a protein phosphatase, regulated the phosphorylation of SRSF3 in hepatocellular carcinoma (HCC) and contributed to the proliferation, invasion, and metastasis of HCC." (PMID 34290239, 2021). "Besides the tumor promoting role, a recent study found that SRSF3 might function as a suppressor of hepatic carcinogenesis, because mice with hepatocyte-specific knockout of Srsf3 invariably developed hepatocellular carcinoma at late ages." (PMID 26282282, 2015). "In contrast, we found seven out of nine mice with liver Srsf3 KO, but only one of 15 mice bearing WT Srsf3 with DEN injection, developed pathological hepatocellular carcinoma at the 6th month of mice age." (PMID 40568073, 2025). "Competitive binding between HNRNPH1 and SRSF3 to PRMT5 pre-mRNA promotes PRMT5-ISO5 production and increases radiosensitivity in hepatocellular carcinoma cells." (PMID 38405130, 2024). "Amiloride, a diuretic, induces hypo-phosphorylation and downregulation of SRSF3 and SRSF1, leading to alteration of RNA splicing patterns in many genes and cell cycle disruption in hepatocellular carcinoma cells." (PMID 37416784, 2023). "While SRSF3 mRNA is increased, the significant reduction of SRSF3 protein, not other SR proteins, being accompanied by induction of DNA damage in hepatocellular carcinoma, appears to be related to IGF2 overexpression and activation of AKT and ERK signaling." (PMID 37416784, 2023).
colon cancer (13 papers, 2013 to 2024). "Loss of SRSF3 in human colon cancer cells induces an increasing in the ratio of PKM1/PKM2, leading to a metabolic shift from glycolysis toward oxidative phosphorylation." (PMID 33072610, 2020). "Activation of Wnt signaling pathway by Wnt3a protein significantly increases SRSF3 expression in colon cancer cells." (PMID 37416784, 2023). "In HCT116 colon cancer cells, SRSF3 knockdown induces G1 cell cycle arrest due to the downregulation of cyclin D1 and E2F1, which are essential for G1-to-S cell cycle progression." (PMID 37416784, 2023). "Oxidative stress-induced by arsenite inhibits NMD to promote stability of SRSF3 isoform RNA with exon 4 inclusion in a human colon cancer cell line, HCT16 cells." (PMID 37416784, 2023). "SRSF3 regulates the cell growth and maintenance energy metabolism of colon cancer cells through PKM splicing." (PMID 35715407, 2022). "The silencing of SRSF3 in human colon cancer cells induced a marked growth inhibition in both in vitro and in vivo experiments and caused an increase in the PKM1/PKM2 ratio, thus resulting in a metabolic shift from glycolysis to oxidative phosphorylation." (PMID 30279379, 2018). "Intracellular levels of SRSF3 mRNA are important for cancer cells: siRNA-mediated downregulation of SRSF3 leads to cell cycle arrest at G1 in colon cancer cells, and their increased death through apoptosis." (PMID 23935626, 2013). "In addition to the G2/M phase transition, SRSF3 plays an important role of in regulating the progression of the G1/S phase transition in colon cancer cells." (PMID 32284746, 2020). "In this way, depletion of SRSF3 promotes the apoptosis of colon cancer cells." (PMID 32284746, 2020). "Similarly, in CD133+ colon cancer stem like cells (CSLCs), SRSF3 was overexpressed and acted a part in the oncogenicity of colon CSLCs by regulation of the Wnt/b-catenin pathway." (PMID 33072610, 2020). "Other SR proteins like SRSF3 (SRp20) and SRSF6 have been classified as proto-oncogenes as well, mostly in lung and colon cancers." (PMID 35979354, 2022). "Through flow cytometric analysis, we found that knockdown of SRSF3 increased the cell population in the G2/M phase in SW480, a colon cancer cell line, and U2OS, a bone cancer cell line." (PMID 36344491, 2022). "SRSF3, as a novel target of the Wnt/b-catenin pathway, was upregulated by Wnt pathway activation in CD133+ colon cancer cells." (PMID 33072610, 2020). "SRSF3 regulates alternative splicing of HIPK2 exon 8 to prevent HIPK2-related apoptosis 114, but increases the production of anti-apoptotic protein BCL2 in colon cancer cells." (PMID 37416784, 2023). "β-catenin is a central mediator of Wnt signaling pathway and CD133+ (a stemness marker for cancer stem cells) colon cancer stem cells express more SRSF3 than CD133- non-stem cancer cells." (PMID 37416784, 2023).
glioblastoma (13 papers, 2012 to 2025). The most malignant astrocytic tumor (WHO grade IV). "Recent studies have suggested that SRSF3 is a significant regulator of glioblastoma-related alternative splicing and is directly associated with glioblastoma development, progression, aggressiveness and patient survival." (PMID 35198444, 2022). "SRSF3, a potential exonic splicing enhancer that is upregulated in glioblastoma, binds to the CA(G/C/A)CC(C/A) motif and alters more than 1,000 alternative splicing events." (PMID 37875914, 2023). "In glioblastoma, SRSF3 promotes the exon 7 inclusion of ETV1 and mutually exclusive of the exon 9 of NDE1 to promote tumorigenesis." (PMID 37558679, 2023). "Functional SRSF3 in glioblastoma cells U-87 MG and U-118 MG is related to PDGFRB-activated PI3K-AKT-ERK pathway." (PMID 37416784, 2023). "Overexpressing circSMARCA5 in glioblastoma multiforme cells significantly decreases their migration via regulating the SRSF1/SRSF3/PTB axis." (PMID 30956729, 2019). "A circRNA derived from SMARCA5 gene, cicrSMARCA5 which is not characterized carefully with unknown copy number and cellular locations, appears to increase the inclusion of SRSF3 exon 4 in glioblastoma cells." (PMID 37416784, 2023). "In glioblastoma cells representing another hard-to-treat cancer type, siRNA-mediated or CRISPR/Cas9-mediated inhibition of SRSF3 has been shown to suppress their tumorigenic phenotypes." (PMID 40568080, 2025). "For instance, in glioblastoma, tumorigenic RBP SRSF1 was found to bind to circSMARCA5 at multiple sites, with this circRNA functioning as a tumor suppressor, regulating the activity of SRSF1/SRSF3/PTB axis and preventing tumor angiogenesis and migration." (PMID 37835380, 2023). "This indicates that there is a positively correlation between the SRSF3 Ex4/SRSF3 No Ex4 ratio and the expression levels of circSMARCA5 in glioblastoma biopsies." (PMID 33072610, 2020). "To objectively compare the performance of ASOs targeting the 10W region versus those targeting the previously characterized SRSF3 region, we did side-by-side ASO transfections at different doses, with final concentrations of 30, 60 or 90 nM in the glioblastoma cell lines A172 and U87-MG." (PMID 23155487, 2012). "CircSMARCA5 inhibits glioblastoma multiforme (GBM) cell migration by sequestering serine and arginine rich splicing factor 1 (SRSF1) that enhances exon 4 skipping in SRSF3 pre-mRNA." (PMID 33317550, 2020).
glioma (13 papers, 2018 to 2025). A benign or malignant brain and spinal cord tumor that arises from glial cells (astrocytes, oligodendrocytes, ependymal cells). "SRSF3 is often upregulated in clinical glioma specimens, and it has been demonstrated that high SRSF3 is associated with tumor progression and a bad prognosis for glioma patients." (PMID 40129567, 2025). "Another splicing factor contributing to this metabolic switch is the SR protein SRSF3, which is also up-regulated in gliomas and sustains glioma stem cells (GSCs) growth, self-renewal, and tumorigenicity." (PMID 31861467, 2019). "The suppressive effects of amiodarone on the SRSF3 promoter activity were also verified in two glioma cell lines, GBM8401 and U118MG." (PMID 29568365, 2018). "Additionally, SRSF3 is expressed at higher levels in glioma, and it may act as a positive regulator of SRSF1‐dependent glioma cell migration." (PMID 39239069, 2024). "CircSMARCA5 affects the malignant behavior of glioma by regulating serine and arginine rich splicing factor 1 (SRSF1)/SRSF3/PTB." (PMID 34249673, 2021). "Previous studies have demonstrated that most SRSFs were extensively dysregulated with oncogenic roles through regulating the AS of various cancer-related genes in many cancers such as lung (SRSF1, SRSF5), breast (SRSF3), colon (SRSF1, SRSF10), liver cancers (SRSF2), and glioma (SRSF1, SRSF3)." (PMID 37558679, 2023). "Moreover, higher levels of splicing factor 3 (SRSF3) expression are observed in glioma and it has been speculated to function as a positive regulator of SRSF1-dependent glioma cell migratory activity." (PMID 37122733, 2023). "Interestingly, SRSF3 is known to interplay with two other splicing factors, polypyrimidine tract binding protein 1 (PTBP1) and polypyrimidine tract binding protein 2 (PTBP2), that positively regulate glioma cells migration." (PMID 29415469, 2018).
oral squamous cell carcinoma (12 papers, 2015 to 2025). "In this study, we used oral squamous cell carcinoma (OSCC) as a model to investigate the potential causes of SRSF3 overexpression." (PMID 26416554, 2015). "SRSF5 and SRSF3 were reported to be overexpressed in oral squamous cell carcinoma (OSCC), and necessary for OSCC cell proliferation, cell cycle progression, and in vivo tumor formation." (PMID 40938473, 2025). "A previous study demonstrated that SRSF3 is an autophagy suppressor in oral squamous cell carcinoma cell lines." (PMID 36764525, 2023). "HnRNP L promotes SRSF3 full-length protein expression also by inhibiting exon 4 inclusion in oral squamous cell carcinoma cells." (PMID 37416784, 2023). "Knockdown of SRSF3 induces significant cellular autophagic activity, whereas SRSF3 overexpression inhibits autophagy in oral squamous cell carcinoma cells." (PMID 37416784, 2023). "We found that the inclusion of SRSF3 exon 4 is impaired in oral squamous cell carcinoma (OSCC) cells." (PMID 26416554, 2015). "In oral squamous cell carcinoma (OSCC) cells, PTBP1 and PTBP2 bind to an ESS motif in exon 4 of SRSF3 and inhibit its inclusion, leading to overexpression of full-length functional SRSF3." (PMID 38302461, 2024). "It has been reported that SRSF3 regulates the expression of PTBP1 and PTBP2 in HEK-293 (human embryonic kidney epithelial cell) and CAL 27 (oral squamous cell carcinoma) cells." (PMID 30279379, 2018). "In oral squamous cell carcinoma cells, polypyrimidine tract binding protein (PTBP) 1 and PTBP2 were shown to bind to exonic splicing suppressors of SRSF3 exon 4 to prevent its inclusion, leading to the upregulation of full-length SRSF3 (SRSF3-FL)." (PMID 38909100, 2024).
cervical carcinoma (10 papers, 2017 to 2025). A carcinoma arising from either the exocervical squamous epithelium or the endocervical glandular epithelium. "It has been shown that the high expression of SRSF3 in cervical cancer promotes the generation of the oncogenic spliceosomes DDX5-L and inhibits the generation of the suppressor spliceosome DDX5-S." (PMID 40129567, 2025). "In this study, we aimed to investigate the mRNA and protein expression levels of SRSF3-FL and SRSF3-PTC under normal conditions or under stress in human cervical cancer cells." (PMID 38909100, 2024). "On the migration of cervical cancer SiHa and HeLa cells via transwell utilizing, the consequence of SRSF3 was surveyed." (PMID 36237584, 2022). "In cervical cancer cells, RNA interference technology was utilized to lessen the SRSF3 level, and via RT-PCR utilization, the SRSF3 level in every group of cells was revealed." (PMID 36237584, 2022). "Reducing the SRSF3 level can restrain the viability and metastasis of cervical cancer cells via restraining the PI3K/AKT/mTOR signaling pathway." (PMID 36237584, 2022). "In this report, we first describe SRSF3 as a novel target of theophylline against breast and cervical cancer cell growth." (PMID 29254178, 2017).
liver disease (8 papers, 2020 to 2026). "SRSF3 reduction contributes to progressive liver disease, and mice with SRSF3 KO developed liver cancer with aging, suggesting a possible tumor suppressive effect of SRSF3." (PMID 40568073, 2025). "In all three studies, enrichment of SRSF3-dependent SEs was seen with NAFLD (NAS, steatosis, ballooning) but not in NASH (fibrosis, inflammation) suggesting that changes in SRSF3-dependent splicing occur early in liver disease." (PMID 38291075, 2024). "Under oxidative stress induced by palmitic acid, NEDD8 promotes the neddylation of SRSF3 at 11 lysine sites, resulting in SRSF3 degradation in liver diseases." (PMID 32284746, 2020). "SRSF3 is regulated in a neddylation-dependent manner in the liver, which provides an effective therapeutic strategy for suppressing liver diseases and hepatocellular carcinogenesis." (PMID 32284746, 2020). "As SRSF3-dependent SEs were enriched in the changes in RNA splicing during early liver disease, we sought to understand how SRSF3 could contribute to the changes in RNA splicing." (PMID 38291075, 2024). "Aberrant splicing of FN1 may be related to hepatotoxic effects, as downregulated or dysfunctional SRSF3, and subsequent aberrant splicing of its targets including elevated EDA-Fn1, has been associated with liver disease." (PMID 37267159, 2023). "Consequently, it is likely that SRSF3 presents low expression and tumor-suppressor activity in mouse liver disease, while it shows high expression and acts as an oncogene in human HCC, suggesting its role as an unfavorable prognostic predictor in HCC." (PMID 33072610, 2020). "Our data suggested that changes in SRSF3-dependent splicing events could be observed in early liver disease, so we investigated alterations in RNA splicing in three other liver transcriptome datasets to see if SRSF3-dependence correlated with early versus late disease." (PMID 38291075, 2024).